SNORA3A (small nucleolar RNA, H/ACA box 3A)
Synonyms: ACA3; SNORA3; SNORA45A
Gene: Small nucleolar RNA gene on chromosome 11 (8,684,227 to 8,684,356, forward strand). Ensembl gene ENSG00000200983.
Gene Ontology:
Biological process: RNA processing
Cellular component: nucleolus
Homologues: Orthologues: chimpanzee SNORA3A (99% identical), macaque SNORA3A (98% identical), rabbit SNORA3A (95% identical), guinea pig SNORA3A (92% identical), mouse Gm24698 (88% identical), pig SNORA3A (88% identical), rat Snora3A (87% identical), mouse Snora3 (85% identical). Paralogues in human: SNORA3B (66% identical), SNORA3C (60% identical).
Diseases named in the same sentence as SNORA3A in open-access papers:
SNORA3A is named in the same sentence as 5 diseases in open-access papers, as found by Europe PMC text mining. Sharing a sentence is not in itself a finding about the gene and the disease. The quoted sentences say what the papers report.
schizophrenia (1 paper, 2019). A major psychotic disorder characterized by abnormalities in the perception or expression of reality. "Although non-coding RNAs such as small nucleolar RNAs (snoRNAs), microRNAs and long non-coding RNAs (LncRNAs), have been studied in disease etiology, the involvement of SNORA38B, SNORA68, SNORA23, SNORA20, and SNORA3A in the pathogenesis of schizophrenia has yet to be reported." (PMID 30967896, 2019).
SNORA3A also shares sentences with these, for which no sentence is quoted: lung carcinoma (2 papers); cancer (1); glioblastoma (1); tumor (1).